OR2K2 (olfactory receptor family 2 subfamily K member 2)
Description:
Odorant receptor.
Synonyms: OR2AR1P; HTPCRH06; HSHTPCRH06; OR2AN1P
Tractability: Antibody: UniProt places it where antibodies can reach, with medium confidence; UniProt predicts a signal peptide or a membrane-spanning region; its Gene Ontology location is reachable by antibodies, with medium confidence.
Gene: Protein-coding gene on chromosome 9 (111,327,229 to 111,330,224, reverse strand). Ensembl gene ENSG00000171133.
Subcellular location: Cell membrane
Pathways (Reactome):
Sensory Perception: Expression and translocation of olfactory receptors
Gene Ontology:
Molecular function: olfactory receptor activity; G protein-coupled receptor activity
Biological process: detection of chemical stimulus involved in sensory perception of smell; G protein-coupled receptor signaling pathway
Cellular component: plasma membrane; membrane
Genetic constraint (gnomAD): Loss-of-function variants: 9 observed, 16.68 expected, observed/expected ratio (o/e) 0.54, 90% interval 0.32 to 0.94. The upper end of that interval is the gene's LOEUF score, 0.94, which puts it in group 3 of 6, group 1 being the genes least tolerant of losing a copy. Missense variants: 389 observed, 400.76 expected, observed/expected ratio (o/e) 0.97, 90% interval 0.89 to 1.06. Synonymous variants: 151 observed, 157.65 expected, observed/expected ratio (o/e) 0.96, 90% interval 0.84 to 1.1.
Homologues: Orthologues: chimpanzee OR2K2 (98% identical), macaque OR2K2 (95% identical), mouse Or2k2 (86% identical), pig OR2K2 (85% identical), rat Or2k2 (85% identical), guinea pig OR2K2 (81% identical). Paralogues in human: OR13D1 (61% identical), OR13C9 (57% identical), OR2S2 (56% identical), OR13C2 (56% identical), OR13C3 (55% identical), OR13C4 (55% identical), OR13C5 (54% identical), OR13C8 (53% identical), OR13J1 (52% identical), OR2F1 (51% identical), OR2G3 (51% identical), OR2F2 (48% identical), and 80 more.
Diseases named in the same sentence as OR2K2 in open-access papers:
OR2K2 is named in the same sentence as 2 diseases in open-access papers, as found by Europe PMC text mining. Sharing a sentence is not in itself a finding about the gene and the disease. The quoted sentences say what the papers report.
frontotemporal dementia (1 paper, 2024). Frontotemporal dementia (FTD) comprises a group of neurodegenerative disorders, characterized by progressive changes in behavior, executive dysfunction and language impairment, as a result of degeneration of the medial prefrontal and frontoinsular cortices. "In a more recent gene expression study encompassing healthy controls, advanced AD (Braak stage III–VI), frontotemporal dementia, and Huntington’s disease (GSE110226), OR2K2 was indeed found to be expressed in the CP." (PMID 38540444, 2024).
OR2K2 also shares sentences with these, for which no sentence is quoted: Huntington disease (1 paper).